HS6ST2 (heparan sulfate 6-O-sulfotransferase 2)
Description:
6-O-sulfation enzyme which catalyzes the transfer of sulfate from 3'-phosphoadenosine 5'-phosphosulfate (PAPS) to position 6 of the N-sulfoglucosamine residue (GlcNS) of heparan sulfate.
Synonyms: HS6ST-2; MRXSPM
Tractability: Antibody: UniProt predicts a signal peptide or a membrane-spanning region; the Human Protein Atlas places it where antibodies can reach.
Gene: Protein-coding gene on chromosome X (132,626,015 to 132,961,395, reverse strand). Ensembl gene ENSG00000171004.
Subcellular location: Membrane
Subcellular location (Human Protein Atlas): Golgi apparatus; Plasma membrane
Pathways (Reactome):
Metabolism: HS-GAG biosynthesis
Gene Ontology:
Molecular function: heparan sulfate 6-sulfotransferase activity; sulfotransferase activity
Biological process: heparan sulfate proteoglycan biosynthetic process
Cellular component: Golgi membrane; Golgi apparatus; membrane
Homologues: Orthologues: chimpanzee HS6ST2 (99% identical), macaque HS6ST2 (98% identical), guinea pig HS6ST2 (92% identical), rabbit HS6ST2 (92% identical), pig HS6ST2 (92% identical), rat Hs6st2 (92% identical), dog HS6ST2 (91% identical), mouse Hs6st2 (87% identical), tropical clawed frog hs6st2 (53% identical), zebrafish hs6st2 (42% identical), Drosophila melanogaster Hs6st (28% identical), Caenorhabditis elegans hst-6 (24% identical). Paralogues in human: HS6ST3 (41% identical), HS6ST1 (38% identical).
Diseases named in the same sentence as HS6ST2 in open-access papers:
HS6ST2 is named in the same sentence as 66 diseases in open-access papers, as found by Europe PMC text mining. Sharing a sentence is not in itself a finding about the gene and the disease. The quoted sentences say what the papers report.
gastric cancer (5 papers, 2013 to 2023). A primary or metastatic malignant neoplasm involving the stomach. "For example, the expression of HS6ST2 was up-regulated in tumors of gastric cancer, and related to the poor prognosis." (PMID 33836688, 2021). "The second transcript was heparin sulfate 6-O-sulfotransferase 2 (HS6ST2), which affects adhesion and migration and its expression has furthermore been correlated to poor prognosis and reduced survival in gastric cancer." (PMID 30555629, 2018). "Gastric cancer patients with increased SERPINE1 and HS6ST2 expression had unfavorable prognoses (p = 0.000035 and p = 0.009, respectively), suggesting these as potential drug targets." (PMID 35954218, 2022). "Gastric cancer patients with increased SERPINE1 and HS6ST2 expression had unfavorable prognoses, suggesting these as potential drug targets." (PMID 35954218, 2022). "We performed a drug-target prediction analysis using the Genomics of Drug Sensitivity in Cancer (GDSC) database and identified candidate drugs (ZG10, Dasatinib, CGP-082996) for HS6ST2, RPS19, and SERPINE1 in gastric cancer." (PMID 35954218, 2022).
lung carcinoma (4 papers, 2013 to 2023). "In present study, the FAM83H-AS1/miR-545-3p/HS6ST2 axis was assumed a novel signaling pathway associated with lung cancer progression and its in-depth molecular mechanism was investigated." (PMID 35260044, 2022). "In lung cancer, lncRNA FAM83H-AS1 was inversely associated with miR-545-3p expression in lung cancer samples and lncRNA FAM83H-AS1 regulates the HS6ST2 protein by targeting miR-545-3p." (PMID 36787056, 2023). "Adequate findings on COL10A1 and NQO1 in lung cancer have been reported; therefore, HS6ST2 was identified as our gene of interest." (PMID 35260044, 2022). "Specifically, HS6ST2 is involved in the pathogenesis of malignant tumors and up regulated in different tumor types, such as thyroid, colorectal, and lung cancers." (PMID 35260044, 2022). "For the first time, we report HS6ST2 as a potential target of miRNA-545-3p and elucidate its role in lung cancer proliferation." (PMID 35260044, 2022). "In conclusion, our data provide a novel target for miRNA-545-3p and HS6ST2 and elucidate the potential role of HS6ST2 in lung cancer proliferation." (PMID 35260044, 2022). "The expression level of FAM107A is decreased in patients with NSCLC, whereas the high levels of expression of HS6ST2 are observed in lung cancer cell lines." (PMID 30453959, 2018). "High levels of HS6ST2 mRNA expression were also observed in colorectal, esophageal and lung cancer cell lines." (PMID 24649258, 2013). "Also, HS6ST2 has been found to be overexpressed in lung cancer and is identified as an inferior prognosticator." (PMID 35260044, 2022). "We further investigated the role of HS6ST2 in lung cancer progression." (PMID 35260044, 2022). "Additionally, understanding the significance of miR-545-3p and HS6ST2 in lung cancer pathogenesis would provide a valuable theoretical basis for the diagnosis and treatment of NSCLC." (PMID 35260044, 2022). "Moreover, inhibition of miR-545-3p promoted HS6ST2 protein expression and lung cancer cell invasion." (PMID 35260044, 2022). "In the present study, we found that HS6ST2 silencing reduced the proliferative and invasive phenotypes of NSCLC cells, suggesting its role in promoting lung cancer malignancy." (PMID 35260044, 2022). "However, HS6ST2 expression, regulation, and clinical significance in lung cancer have not yet been elucidated." (PMID 35260044, 2022).
colorectal cancer (2 papers, 2013 to 2019). A primary or metastatic malignant neoplasm that affects the colon or rectum. "It was demonstrated that the heparan sulfate D-glucosaminyl 6-O-sulfotransferase-2 (HS6ST2) gene is overexpressed in colorectal cancer (CRC) and its clinical significance in patients with CRC was investigated." (PMID 24649258, 2013). "HS6ST2 was responsible for angiogenesis in colorectal cancer." (PMID 30970615, 2019).
esophageal cancer (2 papers, 2013 to 2023). A primary or metastatic malignant neoplasm involving the esophagus. "HS6ST2 correlated favorably with the degree to which genes were silenced in uterine corpus endometrial carcinoma, uveal melanoma, lymphoid neoplasm diffuse large b-cell lymphoma, and esophageal carcinoma." (PMID 37932473, 2023). "HS6ST2 was highly expressed in bladder urothelial carcinoma (BLCA), cholangiocarcinoma (CHOL), pheochromocytoma and paraganglioma (PCPG), colon adenocarcinoma (COAD), esophageal carcinoma (ESCA), LUAD, thyroid carcinoma (THCA), and lung squamous cell carcinoma (LUSC)." (PMID 37932473, 2023).
glioma (2 papers, 2017 to 2023). A benign or malignant brain and spinal cord tumor that arises from glial cells (astrocytes, oligodendrocytes, ependymal cells). "In contrast, in rectum adenocarcinoma and brain lower grade glioma, HS6ST2 expression was inversely correlated with the porphyrin and chlorophyll metabolism pathways and the metabolism of xenobiotics by cytochrome P450, while the correlation was positive in head and neck squamous cell carcinoma." (PMID 37932473, 2023).
Insulin resistance (2 papers, 2023 to 2025). Increased resistance towards insulin, that is, diminished effectiveness of insulin in reducing blood glucose levels. "Targeted disruption of Hs6st2 causes obesity and insulin resistance in aged male mice." (PMID 41072794, 2025).
Obesity (2 papers, 2022 to 2025). Accumulation of substantial excess body fat. "The first signal, rs1328056 (P = 3.6 × 10−8), is an intronic variant in the HS6ST2 gene, which has been associated with obesity and impaired glucose metabolism in mouse studies." (PMID 35902682, 2022).
renal cell carcinoma (2 papers, 2018 to 2023). "Furthermore, HS6ST2 can be downregulated by miR-145-5p, limiting the development of renal cell carcinoma (RCC) cells." (PMID 37932473, 2023). "In renal cell carcinoma cell lines miR-145-5p is dysregulated and several targets, including e2F-associated phosphoprotein (EAPP), Heparan Sulfate 6-O-Sulfotransferase 2 (HS6ST2), Lysyl Oxidase (LOX), Transforming Growth Factor beta-2 (TGFB2) and Vaccinia-related Kinase 2 (VRK2), were confirmed." (PMID 30102719, 2018).
acute myeloid leukemia (1 paper, 2023). Acute myeloid leukemia (AML) is a group of neoplasms arising from precursor cells committed to the myeloid cell-line differentiation. "HS6ST2 expression was lower in acute myeloid leukemia (LAML), adrenocortical carcinoma (ACC), ovarian serous cystadenocarcinoma (OV), pancreatic adenocarcinoma (PAAD), KICH, KIRC, KIRP, and stomach adenocarcinoma (STAD) but higher in the other 11 tumors." (PMID 37932473, 2023).
adrenocortical carcinoma (1 paper, 2023). "HS6ST2 was found to be a protective factor in bladder urothelial carcinoma and a risk factor in kidney renal papillary cell carcinoma, stomach adenocarcinoma, adrenocortical carcinoma, and according to Cox regression analyses." (PMID 37932473, 2023).
bladder urothelial carcinoma (1 paper, 2023). "As determined by KM OS analysis, HS6ST2 was a protective factor for patients with bladder urothelial carcinoma and rectum adenocarcinoma but a risk factor for patients with kidney renal papillary cell carcinoma and uveal melanoma." (PMID 37932473, 2023). "Similarly, KM analysis of DSS uncovered that HS6ST2 was a risk factor in stomach adenocarcinoma, kidney renal papillary cell carcinoma, and uveal melanoma but acted as a protective factor in bladder urothelial carcinoma." (PMID 37932473, 2023). "KM and Cox regression analyses showed that high HS6ST2 expression was associated with worse DFI in lung adenocarcinoma and kidney renal papillary cell carcinoma and with better DFI in bladder urothelial carcinoma." (PMID 37932473, 2023). "The Toll-like receptor signaling pathway was negatively correlated with HS6ST2 expression in bladder urothelial carcinoma and pancreatic adenocarcinoma." (PMID 37932473, 2023).
breast invasive carcinoma (1 paper, 2023). "HS6ST2 was found to be significantly linked with the infiltrating levels of naive B cells across cancers in the TCGA data, particularly in breast invasive carcinoma, brain lower grade glioma, and ovarian serous cystadenocarcinoma." (PMID 37932473, 2023). "The results show that HS6ST2 was highly expressed in most cancers but lower in Breast invasive carcinoma, Kidney Chromophobe, Kidney renal clear cell carcinoma, Kidney renal papillary cell carcinoma, and Uterine Corpus Endometrial Carcinoma." (PMID 37932473, 2023). "In lung squamous cell carcinoma, testicular germ cell tumors, and thymoma, the number of M2 macrophages penetrating a tissue was strongly linked with HS6ST2 expression; however, in breast invasive carcinoma, the correlation was negative." (PMID 37932473, 2023). "In contrast, tumor tissues had lower levels of HS6ST2 than healthy tissues in breast invasive carcinoma (BRCA), kidney renal papillary cell carcinoma (KIRP), uterine corpus endometrial carcinoma (UCEC), kidney renal clear cell carcinoma (KIRC), and kidney chromophobe (KICH)." (PMID 37932473, 2023). "In addition, HS6ST2 was favorably connected with steroid hormone biosynthesis and drug metabolism in breast invasive carcinoma, while the correlation was negative in lung adenocarcinoma and brain lower grade glioma." (PMID 37932473, 2023).
breast tumor (1 paper, 2023). "Silencing of HS6ST2 reduced the transcriptional activity mediated by Smad2/3/4, thereby inhibiting the production of IL-11 induced by TGF-β, resulting in the inhibition of breast tumor growth." (PMID 37932473, 2023).
cholangiocarcinoma (1 paper, 2023). A carcinoma that arises from the intrahepatic biliary tree (intrahepatic cholangiocarcinoma) or from the junction, or adjacent to the junction, of the right and left hepatic ducts (hilar cholangiocarcinoma). "In contrast, HS6ST2 was negatively correlated with epithelial cell differentiation in lung adenocarcinoma, but the correlation was positive in cholangiocarcinoma and mesothelioma." (PMID 37932473, 2023).
chondrosarcoma (1 paper, 2018). A malignant cartilaginous matrix-producing mesenchymal neoplasm arising from the bone and soft tissue. "They showed increased HS6ST1 and HS6ST2 expression during chondrosarcoma progression." (PMID 30544937, 2018).
cyst (1 paper, 2023). A sac-like closed membranous structure that may be empty or contain fluid or amorphous material. "Immunohistochemistry showed that HS6ST2 was specifically expressed in bronchial epithelial cells, including IPF lung honeycomb cyst lining cells." (PMID 36681777, 2023).
lung adenocarcinoma (1 paper, 2023). A carcinoma that arises from the lung and is characterized by the presence of malignant glandular epithelial cells. "Firstly, we utilized the Western Blot technique to assess the expression levels of the HS6ST2 protein in lung adenocarcinoma tissue compared to the corresponding adjacent normal tissue." (PMID 37932473, 2023). "The results indicated that the expression of HS6ST2 protein in lung adenocarcinoma tissue was significantly higher than in the corresponding adjacent normal tissue (**p < 0.01)." (PMID 37932473, 2023). "Furthermore, we employed immunohistochemistry experiments to analyze the expression level of HS6ST2 in lung adenocarcinoma samples." (PMID 37932473, 2023). "The biological function of HS6ST2 in cancers was examined by employing gene set enrichment analysis (GSEA), and the results were verified with in vitro experiments with lung adenocarcinoma (LUAD) cell lines." (PMID 37932473, 2023). "The mRNA expression level of HS6ST2 in lung adenocarcinoma tissue was notably higher than in normal tissue (***p < 0.001)." (PMID 37932473, 2023).
melanoma (1 paper, 2024). A malignant, usually aggressive tumor composed of atypical, neoplastic melanocytes. "A375 TFCP2 knockout human melanoma cells have decreased expression of HS3ST3A1 and HS6ST2 and increased expression of SULF1 and SULF2 what allowed the authors to state TFCP2 as a novel transcriptional regulator of HS biosynthesis." (PMID 39318629, 2024).
myopia (1 paper, 2019). "We detected a novel pathogenic variant of the X‐linked HS6ST2 gene associated with a very unusual combination of syndromic ID and severe congenital myopia." (PMID 30471091, 2019).
non-small cell lung carcinoma (1 paper, 2022). A group of at least three distinct histological types of lung cancer, including non-small cell squamous cell carcinoma, adenocarcinoma, and large cell carcinoma. "FAM83H-AS1 favors non-small cell lung cancer by targeting the miR-545-3p/HS6ST2 axis, supporting the possibility of developing FAM83H-AS1 as a target for NSCLC intervention." (PMID 35260044, 2022).
ovarian carcinoma (1 paper, 2007). A malignant neoplasm originating from the surface ovarian epithelium. "We extended these studies by examining the distribution of the mRNA for 2-O-sulphotransferase and this closely mirrored that seen with the HS6ST2 mRNA, again suggesting that sulphated HS was made by ovarian cancer cells (data not shown)." (PMID 17437011, 2007).
Paganini-Miozzo syndrome (1 paper, 2025). A X-linked, syndromic, neurodevelopmental disorder characterized by intellectual disability, global developmental delay, severe myopia, and mild facial dysmorphism. "Paganini-Miozzo syndrome (MRXSPM) is a globally rare disease caused by hemizygous mutations in the HS6ST2 gene on chromosome Xq26." (PMID 40686562, 2025). "Using WES analysis, we identified a novel hemizygous single-nucleotide variant, c.764C>A (p.Pro255Glu), in Paganini-Miozzo syndrome-related gene HS6ST2 (NM_001077188.1, ENST00000521489.5) on chromosome Xq26.2 of the proband." (PMID 40686562, 2025).
pancreatic adenocarcinoma (1 paper, 2023). "Cox regression analysis showed that HS6ST2 over-expression was associated with better PFI in pancreatic adenocarcinoma and thymoma but associated with poor PFI in uveal melanoma." (PMID 37932473, 2023). "Positive correlations were found between HS6ST2 expression and the cytosolic DNA sensing pathway and antigen processing and presentation in prostate adenocarcinoma, skin cutaneous melanoma, and stomach adenocarcinoma, but the correlations were negative in pancreatic adenocarcinoma." (PMID 37932473, 2023).
pancreatic cancer (1 paper, 2013). "As regards the biological function of HS6ST2, activation of HS6ST2 was observed in pancreatic cancer cells and the gene silencing of endogenous HS6ST2 expression inhibited cell growth, invasion, migration and tumorigenicity." (PMID 24649258, 2013).
pulmonary fibrosis (1 paper, 2023). Chronic progressive interstitial lung disorder characterized by the replacement of the lung tissue by connective tissue, leading to progressive dyspnea, respiratory failure, or right heart failure. "Like HS6ST2, ADAMTS14 is also mainly present in extracellular matrix, which may suggest that the composition or structure of extracellular matrix is also an important pathological factor that should not be ignored in pulmonary fibrosis." (PMID 36681777, 2023).
renal clear cell cancer (1 paper, 2023). "HS6ST2 expression was found to be negatively related to OS and was an independent prognostic factor for clear cell renal cell carcinoma patient outcomes." (PMID 37932473, 2023).
sarcoma (1 paper, 2023). A usually aggressive malignant neoplasm of the soft tissue or bone. "The findings showed a positive association between the expression of KDR and ULBP1 and HS6ST2 expression in 11 different types of cancer (in particular, kidney renal papillary cell carcinoma, sarcoma, skin cutaneous melanoma, thyroid carcinoma, and uterine corpus endometrial carcinoma)." (PMID 37932473, 2023).
testicular germ cell tumor (1 paper, 2023). A germ cell tumor arising from the testis. "HS6ST2 expression was positively correlated with stromal scores in testicular germ cell tumors and thymoma and inversely correlated with immune scores, respectively." (PMID 37932473, 2023).
thyroid cancer (1 paper, 2023). "For instance, HS6ST2 is overexpressed in thyroid cancer, and HS6ST2 overexpression is correlated with the progression of thyroid cancer." (PMID 37932473, 2023).